GULP1 (GULP PTB domain containing engulfment adaptor 1)
Description:
May function as an adapter protein. Required for efficient phagocytosis of apoptotic cells. Modulates cellular glycosphingolipid and cholesterol transport. May play a role in the internalization and endosomal trafficking of various LRP1 ligands, such as PSAP. Increases cellular levels of GTP-bound ARF6.
Synonyms: CED6; GULP; CED-6
Tractability: PROTAC: ubiquitination databases record sites on it.
Gene: Protein-coding gene on chromosome 2 (188,291,105 to 188,595,943, forward strand). Ensembl gene ENSG00000144366.
Subcellular location: Cytoplasm
Subcellular location (Human Protein Atlas): Vesicles
Gene Ontology:
Biological process: phagocytosis, engulfment; apoptotic process; phagocytosis
Cellular component: cytoplasm
Homologues: Orthologues: chimpanzee GULP1 (100% identical), dog GULP1 (96% identical), guinea pig GULP1 (96% identical), rabbit GULP1 (96% identical), macaque GULP1 (93% identical), mouse Gulp1 (92% identical), pig GULP1 (89% identical), rat Gulp1 (86% identical), tropical clawed frog gulp1 (85% identical), zebrafish gulp1a (83% identical), zebrafish gulp1b (71% identical), Caenorhabditis elegans ced-6 (42% identical), and 1 more. Paralogues in human: MAPK8IP1 (21% identical), MAPK8IP2 (16% identical), NOS1AP (10% identical), NUMB (10% identical), DAB2 (10% identical), DAB1 (9% identical), NUMBL (8% identical), C1orf226 (8% identical), FAM43A (8% identical), LDLRAP1 (5% identical), FAM43B (4% identical).
Diseases named in the same sentence as GULP1 in open-access papers:
GULP1 is named in the same sentence as 25 diseases in open-access papers, as found by Europe PMC text mining. Sharing a sentence is not in itself a finding about the gene and the disease. The quoted sentences say what the papers report.
bladder cancer (3 papers, 2021 to 2023). "In bladder cancer specimens, loss of immunoreactivity for GULP1 was more frequently seen in muscle-invasive tumors (85.8%) than in non-muscle-invasive tumors (39.0%)." (PMID 34576193, 2021). "An inverse association between AR and GULP1 expression was seen in bladder cancer cell lines." (PMID 34576193, 2021). "In bladder cancer lines, overexpression or silencing of GULP1, as a tumor suppressor, resulted in reduction or induction, respectively, of cell proliferation, migration, and invasion." (PMID 34576193, 2021). "Next, we assessed the impact of GULP1 expression on sensitivity to CDDP treatment in bladder cancer cells." (PMID 34576193, 2021). "Our DNA microarray analysis in control vs. AR knockdown bladder cancer lines identified GULP1 as a potential target of AR signaling." (PMID 34576193, 2021). "We first examined the expression of GULP1 in four human bladder cancer lines that were known to be AR-negative (i.e., 5637, 647V) or AR-positive (i.e., UMUC3, TCCSUP)." (PMID 34576193, 2021). "We herein determined the relationship between AR activity and GULP1 expression in bladder cancer cells and then assessed the functional role of GULP1 in cisplatin sensitivity." (PMID 34576193, 2021). "Cisplatin is a common therapeutic agent for bladder cancer patients, and a recent study showed that high GULP1 expression enhanced the sensitivity of patients to cisplatin." (PMID 34926452, 2021). "We identified GULP1 as a key downstream effector of AR in modulating CDDP sensitivity in bladder cancer." (PMID 34576193, 2021). "Specifically, AR overexpression/androgen treatment and AR knockdown/anti-androgen treatment reduced and induced, respectively, the levels of GULP1 expression in bladder cancer cells." (PMID 34576193, 2021). "It is thus likely that GULP1 represents a key downstream effector of AR signaling in modulating CDDP sensitivity in bladder cancer." (PMID 34576193, 2021). "Thus, the expression of GULP1 was inversely related to the expression/activity of AR in bladder cancer cells." (PMID 34576193, 2021). "In addition, the expression status of GULP1, along with that of AR, may serve as a predictor of chemosensitivity in patients with bladder cancer." (PMID 34576193, 2021). "The high expression of ABCB9, SPTBN2, GULP1, IGF1, P4HB, NES and DPYSL2 and the low expression of ANXA6, OAS1, RAD9a, DNASE2B and FANCF would be beneficial to the prognosis of bladder cancer patients." (PMID 37845668, 2023). "In the present study, we further investigated the role of GULP1, as a downstream target of AR, in CDDP resistance, using bladder cancer cell lines as well as surgical specimens." (PMID 34576193, 2021). "In particular, it has been documented that GULP1 activates SMAD3 or inactivates AKT/PDK1 and MAPK in ovarian cancer cells, while it inhibits the nuclear translocation of NRF2 and subsequently reduces the expression of HMOX1 in bladder cancer cells." (PMID 34576193, 2021). "In the present study, we aim to investigate whether GULP1, an adaptor protein known to facilitate phagocytosis, represents a downstream effector of AR and thereby modulates CDDP sensitivity in bladder cancer." (PMID 34576193, 2021). "Moreover, GULP1 was suggested to involve CDDP resistance by showing an increase in cell viability and a decrease in apoptosis in a GULP1-silenced bladder cancer T24 line cultured in the presence of 20 μM CDDP, as well as a decrease in GULP1 expression in a CDDP-resistant T24 subline." (PMID 34576193, 2021).
ovarian carcinoma (3 papers, 2020 to 2021). A malignant neoplasm originating from the surface ovarian epithelium. "Consistent with our data, GULP1 expression is associated with outcomes in ovarian cancer patients." (PMID 32631357, 2020). "Nonetheless, in ovarian cancer cells, GULP1 showed inhibitory effects on their proliferation while inducing phospho-SMAD3 or reducing phosphorylation of AKT/PDK1 and MAPK." (PMID 34576193, 2021). "Finally, GULP1 (PTB domain‐containing engulfment adaptor protein 1) has been found to be inactivated in ovarian cancer by promoter methylation, which is inversely correlated with expression." (PMID 34510798, 2021).
emphysema (2 papers, 2022 to 2023). "As well as linked to integrin and TGFβ signaling, GULP1 has been associated with emphysema." (PMID 37276213, 2023).
Alzheimer disease (1 paper, 2017). A progressive, neurodegenerative disease characterized by loss of function and death of nerve cells in several areas of the brain leading to loss of cognitive function such as memory and language. "Recently, we and others have shown that GULP1 PTB domain binds to Alzheimer’s disease amyloid precursor protein (APP)." (PMID 29245900, 2017).
atherosclerosis (1 paper, 2026). A disease characterized by the build-up of fatty material and calcium deposition in the arterial wall resulting in partial or complete occlusion of the arterial lumen. "Utilizing bulk RNA sequencing, six core efferocytosis-related genes (STAB1, ANO5, GULP1, LGR6, SCARF1, and CAMK2G) were identified, which exhibit significant diagnostic potential in atherosclerosis." (PMID 42272635, 2026).
bladder tumors (1 paper, 2021). "In addition, the levels of GULP1 mRNA expression were found to be low (or undetectable) in all nine bladder tumors from patients who did not respond to CDDP therapy but were relatively high in two of six responders." (PMID 34576193, 2021). "While GULP1 activators are not currently available, our data further support the notion that concurrent anti-androgen therapy has the potential of being a means of chemosensitization, especially in male patients with AR-positive bladder tumor." (PMID 34576193, 2021).
glioblastoma (1 paper, 2019). The most malignant astrocytic tumor (WHO grade IV). "We further validated the interaction between Gulp1 and EphB2 using U251 glioblastoma cells that endogenously express both proteins." (PMID 31409653, 2019).
liver cancer (1 paper, 2021). An epithelial or non-epithelial malignant neoplasm that arises from the liver. "We report for the first time that LOC644135, ELN, GULP1, ENSG00000248635, GPM6A, and PI15 are associated with the risk of liver cancer recurrence." (PMID 34956309, 2021).
neuroblastoma (1 paper, 2019). Neuroblastoma (NB) is the most common solid, extracranial childhood tumor. "When SKN neuroblastoma cells, endogenously expressing ephrinBs, were cocultured with EphB2ΔC-GFP+ HeLa donor cells, reverse trogocytosis was observed and endogenous Gulp1 was coimmunoprecipitated with endogenous ephrinBs." (PMID 31409653, 2019).
polycystic ovary syndrome (1 paper, 2021). A disorder that manifests as multiple cysts on the ovaries. "The expression of lnc-GULP1–2:1 was lower in patients with diminished ovarian reserve but substantially elevated in patients with polycystic ovary syndrome." (PMID 33472700, 2021).
retinal degeneration (1 paper, 2017). Degeneration of the retina. "In this study, we observed that GULP1 reduces Aβ production, reduces retinal degeneration, rescues motor dysfunction and improves the life expectancy of the flies." (PMID 29245900, 2017). "Overexpression of GULP1 also reduced APP/BACE-mediated retinal degeneration, rescued motor dysfunction and extended longevity of the flies." (PMID 29245900, 2017).
schizophrenia (1 paper, 2009). A major psychotic disorder characterized by abnormalities in the perception or expression of reality. "To test whether other CED orthologs in human are involved in schizophrenia, we conducted association analyses of the GULP1, ABCA1 and ABCA7 genes that are the human orthologs of the CED-6 and CED-7 genes." (PMID 19721717, 2009). "From these data, we concluded that the GULP1 gene and the apoptotic engulfment pathway are involved in schizophrenia in subjects of European ancestry and multiple genes in the pathway may interactively increase the risks to the disease." (PMID 19721717, 2009). "In this study, we provide genetic evidence that the GULP1 gene and the apoptotic engulfment pathway may be involved in schizophrenia." (PMID 19721717, 2009). "Based on these data, we conclude that GULP1 and the CED-1, CED-6 and CED-7 pathway are involved in schizophrenia." (PMID 19721717, 2009).
urothelial carcinoma (1 paper, 2021). A malignant neoplasm derived from the transitional epithelium of the urinary tract (urinary bladder, ureter, urethra, or renal pelvis). "GULP1 is considered to be a tumor suppressor gene, showing anti tumoral function not only in ovarian cells but also in urothelial carcinoma." (PMID 34830991, 2021).
urothelial neoplasm (1 paper, 2021). A neoplasm involving a urothelium. "In the first set of TMA consisting of 129 cases of urothelial neoplasms and corresponding 89 non-neoplastic normal-appearing urothelial tissues, GULP1 was positive in 80 (90%) of non-neoplastic and 96 (74%) of neoplastic specimens." (PMID 34576193, 2021).
cancer (9 papers, 2011 to 2024). A tumor composed of atypical neoplastic, often pleomorphic cells that invade other tissues. "GULP1 expression is significantly decreased in cancer tissue versus normal tissues and highly hypermethylated." (PMID 32631357, 2020). "There are three lncRNAs located close together in the interaction network: NONMMUG034109, NONMMUG021221, and NONMMUG008287; these are involved in the regulation of the mRNA expression of a large number of cancer-related genes, such as Pik3r1, Gulp1, Chrdl1, and Crebaf." (PMID 31947603, 2020). "In the context of cancer, another strongly over-expressed gene (3rd in our list) in the naked mole-rat of potential interest is Gulp1, an adaptor protein that promotes phagocytosis of apoptotic cells, and might therefore contribute to species differences in tissue turnover." (PMID 22073188, 2011). "Among four novel methylation markers in OPSCC (AGTR1, CSGALNACT2, GULP1 and VGF), AGTR1 showed a significant correlation with cancer specificity, HPV infection specificity and p16 + /RB- phenotype." (PMID 36344942, 2022). "GULP1 is located on SSC15 and plays key roles in cancer suppression and immune responses, whereas KBTBD8 is involved in cytoskeleton arrangement, regulation of cell morphology, and idiopathic short stature." (PMID 33705632, 2021). "In line with this study, 43 genes (including CLIP4) were downregulated in ovarian cancer tumor samples and reactivated after treatment with 5-Aza-2'-deoxycytidine (5-aza-dC); CLIP4, GULP1, BAMBI, NT5E, and TGFB2 showed a pattern of cancer-specific methylation." (PMID 33575272, 2020).
tumor (4 papers, 2008 to 2026). "We thus decided to further investigate the functions of GULP1 whose role in neoplastic diseases was largely unknown." (PMID 34576193, 2021). "Finally, there is no information concerning the possible role of deregulated miR-561 and its cognate host gene GULP1 (which codes for an evolutionarily conserved adaptor protein required for efficient engulfment of apoptotic cells by phagocytes) in normal or tumor cells." (PMID 18700954, 2008). "The expression of ANAPC11 was detected in tumor sections by IHC staining, and knockout of ANAPC11 was found to induce increased expression of FOXO3, p21, and GULP1 and decreased expression of Ki67, a well-known marker for cell proliferation." (PMID 37573356, 2023). "GULP1 could result in the rearrangement of the actin cytoskeleton via the MAPK pathway, and GULP1 expression positively regulates TGF-β signaling, leading to the inhibition of tumor cell growth." (PMID 37573356, 2023).
GULP1 also shares sentences with these, for which no sentence is quoted: cardiovascular diseases (1 paper); cutaneous melanoma (1); gynecologic cancer (1); hepatocellular carcinoma (1); infarct (1); ischemia (1); medulloblastoma (1); premature ovarian failure (1); prostate carcinoma (1).